GPER1 (G protein-coupled estrogen receptor 1)
Diseases named in the same sentence as GPER1 in open-access papers (continued):
Sharing a sentence is not in itself a finding about the gene and the disease.
Insulin resistance (18 papers, 2015 to 2025). Increased resistance towards insulin, that is, diminished effectiveness of insulin in reducing blood glucose levels. "Here, we show that GPER1 exerts a beneficial role in insulin resistance, hepatic lipid accumulation, oxidative stress, or inflammation in vivo and in vitro." (PMID 38246352, 2024). "The role of GPER1 in hepatic metabolism has been elucidated in hepatocyte-specific GPER1 knockout female mice, which possess more pronounced high-fat diet induced insulin resistance, hepatic steatosis, hepatic inflammation, and fibrosis compared to GPER1-Flox control female mice." (PMID 40522859, 2025). "In particular, we observed that the lipid accumulation, inflammatory response, fibrosis, or insulin resistance in mouse NAFLD/NASH models were exacerbated by hepatocyte-specific GPER1 knockout but obviously mitigated by hepatic GPER1 activation in female and male mice." (PMID 38246352, 2024). "Notably, HFD-induced glucose homeostasis impairment and systematic insulin resistance were markedly alleviated by the activation of GPER1 with GPER1-specific agonist G1 in female mice." (PMID 38246352, 2024). "Moreover, hepatocyte-specific GPER1 knockout (GPER1-HKO) in female and male mice exacerbated HFD- or high-fat and high-cholesterol (HFHC) diet-induced lipid accumulation, inflammatory response, fibrosis, or insulin resistance in mouse NAFLD/NASH models." (PMID 38246352, 2024).
Cerebral ischemia (16 papers, 2016 to 2025). Restriction of arterial blood supply to the brain associated with insufficient oxygenation to support the metabolic requirements of the tissue. "Recently, GPER1 was suggested to inhibit neuroinflammation in rat cerebral ischemia by regulating microglial phenotypes." (PMID 36835454, 2023). "Intriguingly, selective activation of GPER1 by G1 appeared to increase the infarct volume in male mice subjected to cerebral ischemia, which was accompanied by elevated expression of active caspase-3 in peri-infarct neurons." (PMID 36835454, 2023). "The authors hypothesized that after cerebral ischemia GPER-1 may become the predominant estrogen receptor expressed in brain of male mice, whereas the ERα predominates in female mice." (PMID 34830207, 2021). "GPER-1 could also counteract BBB disruption after brain ischemia." (PMID 34830207, 2021).
thyroid cancer (16 papers, 2011 to 2026). "GPER1 is also known to stimulate cell proliferation in breast, endometrial, ovarian, and thyroid cancer cells by rapid but transient activation of Erk1/235." (PMID 31748686, 2019). "Multiple studies have demonstrated that GPER-1 mRNA and protein levels are significantly upregulated in breast, endometrial, ovarian and thyroid cancers." (PMID 30836961, 2019). "Other than exacerbated proliferation, GPER-1 is involved in several hallmarks of cancer, including stimulated migration and invasion, the metabolic reprogramming, and induction of angiogenesis, in prostate cancer, lung cancer, and thyroid carcinoma." (PMID 30836961, 2019). "For example, estradiol (E2) induces proliferation of BPH-10-3 thyroid cancer cells in a concentration and time-dependent manner, resulting in overexpression of phosphorylation AKT/mTOR; these effects were reversed by G15, a GPER1-specific inhibitor." (PMID 33425895, 2020). "GPER1 expression was described in thyroid carcinoma cell lines but has not been studied yet in normal or benign thyroid tissues or cells." (PMID 25861267, 2015).
cervical carcinoma (15 papers, 2013 to 2026). A carcinoma arising from either the exocervical squamous epithelium or the endocervical glandular epithelium. "Accordingly, this high GPER1 expression is prognostically associated with lower 5-year survival rates in patients with cervical carcinoma." (PMID 37762008, 2023). "In cervical cancer, estrogen signaling persists despite the loss of epithelial estrogen receptor α (ERα) through stromal signaling, alternative ERα isoforms, ERβ, and non-classical receptors such as G protein-coupled estrogen receptor 1 (GPER1)." (PMID 41752059, 2026). "Furthermore, studies have indicated that GPER1 can inhibit tumor formation and metastasis in cervical cancer cells; reducing GPER1 expression may strengthen cervical cancer cell stemness and migration/invasion capabilities." (PMID 37921845, 2023). "Until now, we have not found any studies that discuss the role of GPER1 in the activation of c-fos in cervical cancer cells." (PMID 36231664, 2022). "However, until now, there has been no research into the effects of 17β-EAs in breast and cervical cancer cells due to their binding to GPER1." (PMID 36231664, 2022). "Based on the assumption that the MAPK pathway can induce c-fos, and on the fact that the overexpression of the epidermal growth factor receptor (EGFR) has been reported in cervical cancer cells, we suggest that the modulation of c-fos is not only dependent on GPER1 but also on EGFR." (PMID 36231664, 2022).
colorectal cancer (15 papers, 2017 to 2024). A primary or metastatic malignant neoplasm that affects the colon or rectum. "This study reveals a causal link between (xeno)estrogen-activated GPER1, centriole-positive numerical centrosome amplification, and genomic instability in normal colon and colorectal cancer cells." (PMID 36384894, 2023). "In colorectal cancer, on the other hand, GPER1 appears to act as a tumor suppressor and its expression is negatively correlated with increased tumor stage and lymph node metastasis." (PMID 39252786, 2024). "Moreover, higher GPER1 expression meant survival benefit for colorectal cancer patients." (PMID 39252786, 2024). "The role of the alternate G protein–coupled estrogen receptor 1 (GPER1) in colorectal cancer (CRC) development and progression is unclear, not least because of conflicting clinical and experimental evidence for pro- and anti-tumorigenic activities." (PMID 36384894, 2023).
hepatocellular carcinoma (13 papers, 2016 to 2024). A malignant tumor that arises from hepatocytes. "Hepatocellular carcinoma (HCC) patients' have increased levels of G‐protein‐coupled estrogen receptor (GPER1) compared with nontumor tissue samples." (PMID 32536040, 2020).
pancreatic cancer (12 papers, 2019 to 2025). "In pancreatic cancer, high GPER1 expression has been associated with improved survival, and GPER1 activation leads to peritumoral mesenchymal remodelling in PDAC, reducing fibrous tissue proliferation, inflammation and immunosuppression." (PMID 37921845, 2023). "The clinical candidate AXP107‐11 activates the G‐coupled estrogen receptor 1 (GPER1) enabling a novel therapeutic option to improve chemoefficacy in pancreatic cancer." (PMID 31568691, 2019). "Furthermore, the overexpression of GPER1 in Panc1 permits Dz to bind with ER- Panc1 more efficiently than ER+ MIA-PaCa2 in pancreatic cancer." (PMID 36233347, 2022). "We explored whether GPER1 is expressed in clinical specimens of pancreatic cancer and if it is related to survival." (PMID 31568691, 2019). "GPER1 expression in pancreatic tumors was indicative of survival, and our study proposes that activation of GPER1 may constitute a new avenue for pancreatic cancer therapeutics." (PMID 31568691, 2019). "However, a recent study which used tamoxifen, which also acts as a GPER1 agonist, in a mouse model of pancreatic cancer, found that this could modify the microenvironment and reduce desmoplasia, inflammation, and immune suppression in PDAC." (PMID 31568691, 2019).
dyslipidemia (11 papers, 2015 to 2025). "Although GPER1 expression was undetectable in our mouse liver data, previous reports demonstrated that GPER1 deficiency in male mice leads to dyslipidemia." (PMID 38459198, 2024).
Glucose intolerance (11 papers, 2015 to 2024). Glucose intolerance (GI) can be defined as dysglycemia that comprises both prediabetes and diabetes. "Another example is GPER1, coding for the estrogen receptor, whose functional disturbances result in neuronal dysfunctions, glucose intolerance, increased blood pressure, changed bone mineral density, abnormal joint mobility, and osteoarthritis." (PMID 32366041, 2020). "Only in menopause mice, hippocampal GPER1 expression was positively correlated with glucose intolerance (GTT AUC; p < 0.01), indicating higher hippocampal GPER1 expression was associated with more severe glucose intolerance." (PMID 37221553, 2023).
Cognitive impairment (9 papers, 2020 to 2025). Abnormal cognition is characterized by deficits in thinking, reasoning, or remembering. "Our previous work demonstrates that GPER1 agonists alleviates TBI-induced cognitive impairment and brain edema in mice by regulating microglia-mediated neuroinflammation." (PMID 40605012, 2025). "Signaling mediated by the G-protein coupled estrogen receptor 1, recently targeted for estrogen-related cancer therapy, alleviated cognitive impairment induced by traumatic brain injury via the PI3K/Akt pathway." (PMID 36432439, 2022). "This study is aimed at investigating the potential roles of G protein-coupled estrogen receptor 1 (GPER, also known as GPR30) in the preventive effect of ginsenoside Rg1 against cognitive impairment and hippocampal cell apoptosis in experimental vascular dementia (VD) in mice." (PMID 34899899, 2021). "Our results demonstrate that Gper1 is involved in TBI-induced neuro-apoptosis, neuroinflammation and cognitive impairments in mice." (PMID 40605012, 2025). "Our previous work found that the GPER1 agonist G1 can significantly reduce brain edema and alleviate TBI-induced cognitive impairment in mice." (PMID 40605012, 2025). "We hypothesize that co-therapy with estradiol and a SERMin male TR-BD will reduce affective instability, cognitive impairment, and stress sensitization via selective activation of ER-β/GPER1, without inducing peripheral feminization." (PMID 40995073, 2025).
Parkinson disease (9 papers, 2019 to 2024). A progressive degenerative disorder of the central nervous system characterized by loss of dopamine producing neurons in the substantia nigra and the presence of Lewy bodies in the substantia nigra and locus coeruleus. "In addition, as a novel estrogen membrane receptor, GPER1 also play an important role in mediating immune-related diseases, such as multiple sclerosis, Parkinson’s disease and atherosclerosis-related inflammation." (PMID 39058137, 2024). "Additionally, GPER1 agonist G-1 is protective against inflammation through macrophage modulation in various neuro-diseases, including multiple sclerosis, Parkinson’s disease, and traumatic brain injury." (PMID 38086848, 2023). "An agonist of GPER1 could reduce the enteric macrophage infiltration in a Parkinson's disease mouse model." (PMID 31474980, 2019). "Selective activation of GPER1 appeared to cause neuroprotection in animal models of mood disorders, Alzheimer’s disease, and Parkinson’s disease, but there is no consensus on the role played by GPER1 in ischemic stroke." (PMID 36835454, 2023). "The impact of GPER1 signaling on the brain development and functions is not clear, but GPER1 is highly expressed in the nervous system, and its activation shows beneficial, cell specific effects in various brain disorders (Alzheimer’s, Parkinson’s disease)." (PMID 34089761, 2021).
adrenocortical carcinoma (8 papers, 2015 to 2024). "In adrenocortical cancer, GPER1 presented tumor suppressive properties as GPER1 agonists suppressed adrenocortical carcinoma proliferation via cell cycle arrest, DNA damage, and apoptosis via ERK1/2 activation." (PMID 39252786, 2024). "We previously demonstrated that treatment of the H295R adrenocortical cancer cell line with the non-steroidal, high-affinity GPER (G protein-coupled estrogen receptor 1) agonist G-1 reduced tumor growth in vitro and in vivo through a GPER independent action." (PMID 29383185, 2017).
depression (8 papers, 2013 to 2024). "Studies on rodents have reported that there is an anti-depressant-like effect of estradiol that is mediated by GPER1, leading to the hypothesis that GPER1 might be an innovative target for the treatment of depression." (PMID 33324181, 2020). "Recently, GPER1 was suggested to play roles in E2-mediated effects on mood, as G15 (a GPER1-selective antagonist) attenuated the effects of G1 (GPER1 selective agonist) and E2 in a mouse model of depression, and in cognitive functions such as spatial learning, memory and attention." (PMID 25236887, 2014).
ischemic stroke (8 papers, 2016 to 2025). A stroke disorder caused by obstruction of blood flow to the brain, due to thrombotic (local blood clot formation) or embolic (due to a blood clot or other material traveling from another site) event. "In different types of models, such as ischemic stroke, GPER1 on microglia was also suggested to mediate the effect of decreasing IL-1β and TNF-α under G1 or estradiol stimulation." (PMID 34239558, 2021).
multiple sclerosis (8 papers, 2019 to 2025). A progressive autoimmune disorder affecting the central nervous system resulting in demyelination. "Indeed, the GPER1 specific agonist G1 was found to be beneficial in an animal model of experimental encephalomyelitis and multiple sclerosis, by reducing the severity of the disease and reducing the level of pro-inflammatory cytokines." (PMID 33133022, 2020).
endothelial dysfunction (7 papers, 2012 to 2024). In vascular diseases, endothelial dysfunction is a systemic pathological state of the endothelium (the inner lining of blood vessels) and can be broadly defined as an imbalance between vasodilating and vasoconstricting substances produced by (or acting on) the endothelium. "It protects endothelial cells from inflammation by attenuating G protein-coupled estrogen receptor-1 (GPER-1)-mediated endothelial dysfunction." (PMID 34790246, 2021). "In this study, both agents were used to modulate GPER-1 in vitro and in vivo to investigate the protective role protocatechuic aldehyde (PCA) has in endothelial dysfunction through GPER-1." (PMID 25411835, 2014).
Hepatic steatosis (7 papers, 2015 to 2026). Steatosis is a term used to denote lipid accumulation within hepatocytes. "The GPER1 agonist G1 ameliorates hepatic steatosis via multiple GPER1-dependent mechanisms, including regulating lipid metabolism, suppressing oxidative stress, and reducing apoptosis." (PMID 41929249, 2026). "G1 upregulates GPER1, alleviates hepatocyte steatosis and lipid deposition, modulates lipid metabolism-related proteins, ameliorates hepatic steatosis, and interacts with GAIP-interacting protein C-terminal 1 (GIPC1)." (PMID 41929249, 2026). "In this study, we used various methods to construct metabolic disorder models in female and male mice to comprehensively elucidate the role and potential mechanism of GPER1 in regulating fatty liver." (PMID 38246352, 2024). "Finally, inhibition of AMPK signaling completely blocked the preventive roles of GPER1 activation on hepatic steatosis, inflammation, and fibrosis in female mice." (PMID 38246352, 2024). "Moreover, H&E and Oil Red O staining assays indicated that hepatic GPER1 knockout largely exacerbated hepatic steatosis than the GPER1-Flox control female mice after HFHC feeding." (PMID 38246352, 2024). "First, GPER1-HKO exacerbates HFD and HFHC diet-challenged hepatic steatosis, inflammation, or fibrosis in female and male mice." (PMID 38246352, 2024).
lung adenocarcinoma (7 papers, 2012 to 2024). A carcinoma that arises from the lung and is characterized by the presence of malignant glandular epithelial cells. "GPER1 agonist G1 increased the number of tumour nodules, tumour grade and tumour index in urethane-induced lung adenocarcinoma models." (PMID 37921845, 2023). "The aim of the present study was to examine ERα, ERβ and GPER1 expressions, and to evaluate their correlation with clinicopathologic factors and with the frequency of EGFR and KRAS gene mutations in lung adenocarcinoma." (PMID 35664735, 2022). "However, the role of GPER1, a novel G-protein-coupled estrogen receptor, in the estrogen signaling pathway and the association between its expression and EGFR mutation in lung adenocarcinoma are less well understood." (PMID 35664735, 2022). "Survival analysis further revealed that CRY1, CRY2, GPER1, and FBXL3 were negatively related to survival of lung adenocarcinoma patients, while TIM were positively related to survival." (PMID 37924048, 2023). "Here, we aimed to examine ERα, Erβ, and GPER1 expressions, and to analyze their roles in the mechanism of EGFR-TKIs resistance in lung adenocarcinoma." (PMID 35664735, 2022).
lymph node metastasis (7 papers, 2008 to 2024). "The presence of ulceration and sentinel lymph node metastases were found less frequently in GPER1-positive cases, suggesting that GPER1 may serve as a favorable prognostic marker." (PMID 39252786, 2024).
schizophrenia (7 papers, 2020 to 2026). A major psychotic disorder characterized by abnormalities in the perception or expression of reality. "This positions ER-β/GPER1 agonism as a viable intervention not only for BD, but also for schizophrenia, PTSD, and neurodegenerative conditions—particularly within male subgroups marked by chronic inflammation or monoaminergic instability." (PMID 40995073, 2025). "In a study leveraging an MK-801-induced mouse model of schizophrenia, GPER1 exhibited significant impact on cognitive, learning, and memory functions, thereby suggesting a potential role in the pathogenesis of schizophrenia." (PMID 39905509, 2025). "Furthermore, GPER1’s synaptic localization at glutamatergic terminals modulates cognitive throughput and executive control—targeting core deficits in both schizophrenia and BD." (PMID 40995073, 2025). "In schizophrenia, ER-β and GPER1 play key roles in cognitive and affective symptomatology." (PMID 40995073, 2025). "We conducted this study to test the behavioral changes shown by G protein-coupled estrogen receptor 1 knockout (GPER1 KO) and wild-type (WT) mice with MK-801-induced schizophrenia (SZ)." (PMID 33324181, 2020).
testicular cancer (7 papers, 2014 to 2023). A primary or metastatic malignant neoplasm that affects the testis. "GPER1 is involved in regulating various tumours, such as breast, pancreatic, oesophageal, endometrial, ovarian, cervical, prostate and testicular cancers, as well as lung, liver, thyroid, colorectal and kidney cancers." (PMID 37921845, 2023).
asthma (6 papers, 2015 to 2025). "Here we used the GPER-1 agonist, G1, in ex vivo ILC2 activation assays, to show that activating GPER-1 reduced expression of asthma promoting cytokines from circulating ILC2." (PMID 40821845, 2025). "Although much more work is required for GPER-1 to be clinically applicable, this at least suggests a novel target for limiting the high type 2 (T2) phenotype or eosinophilic endotype of asthma." (PMID 40821845, 2025). "Our hypothesis was that estrogen, acting through GPER-1 would significantly reduce cytokine responses in ILC2 isolated from male and female Veterans with asthma." (PMID 40821845, 2025).